EZH2 (enhancer of zeste 2 polycomb repressive complex 2 subunit)
Diseases named in the same sentence as EZH2 in open-access papers (continued):
Sharing a sentence is not in itself a finding about the gene and the disease.
cancer (continued). "Previous studies have elucidated that enhancer of zeste homolog 2 (EZH2), a histone lysine methyltransferase, plays complex roles in tumorigenesis and cancer development by influencing various cellular processes, including cell cycle progression, autophagy, and apoptosis." (PMID 38264522, 2023). "EZH2 has been shown to repress RUNX3 transcription in cancer cell lines." (PMID 36766749, 2023). "EZH2 overexpression has been linked to the downregulation of epithelial markers, upregulation of mesenchymal counterparts and EMT-associated transcriptional factors in a variety of cancers." (PMID 38031139, 2023). "To date, functions of EZH2 in cells proliferation, senescence, apoptosis and genomic imprinting have been well established, but the concern about its roles in the pathophysiology of cancer is just starting." (PMID 37228649, 2023). "Low expression of EZH2 was observed in Grade I (well differentiated) carcinomas (7/8, 87.5%)." (PMID 37131568, 2023). "Thus, the immunoexpression of EZH2 can be analyzed in Grade 1 carcinomas and can be followed immunohistochemically to see any conversion to higher grade, as Grade 1 shows low expression and Grade 3 shows higher expression of EZH2." (PMID 37131568, 2023). "Thus, immunoexpression of EZH2 in low stage carcinomas can be studied to see any progression to higher stage in advance and this can aid in monitoring the progression and modulating the treatment strategies." (PMID 37131568, 2023). "Among other mechanisms involved, EZH2 contributes to the establishment of a transient repressive chromatin context that enables the DNA repair to proceed, which is the basis for survival of the cancer cell exposed to cisplatin." (PMID 36230683, 2022). "As a novel and potential target for cancer therapy, EZH2 has become extensively researched." (PMID 35208478, 2022). "EZH2 levels were correlated with 21 MHC molecules across cancers." (PMID 35659256, 2022). "To determine whether EZH2 expression levels are correlated with the prognosis of cancer patients, we evaluated the prognostic value of EZH2 in cancer using the GEPIA2 database." (PMID 35627262, 2022). "It is noteworthy that genome stability is affected by EZH2 in cancer cells." (PMID 35236381, 2022). "Furthermore, EZH2 inhibitors can be utilized as adjuvant in synergistic cancer therapy in clinical course." (PMID 35236381, 2022). "For this reason, EZH2 is currently considered a promising target for cancer therapy." (PMID 36362406, 2022). "Immune infiltration analysis revealed a significant correlation between the expression of EZH2 and the abundance of immune cell infiltration, including B cells, CD4+ T cells, CD8+ T cells, macrophages, neutrophils, dendritic cells, and cancer-associated fibroblasts (CAFs), in LIHC tissues." (PMID 35627262, 2022). "The current study analysed EZH2’s effect on cancers prognosis from three databases." (PMID 35659256, 2022). "The transcription activation role of EZH2 has been proposed in cancer." (PMID 36578923, 2022). "EZH2 as the catalytic subunit of polycomb repressive complex 2 (PRC2) represses target genes by H3K27me318, of which the highly activated mutations frequently locate in the early stages of cancer, suggesting a role for activated PRC2 cancer drivers." (PMID 36195655, 2022). "We identified EZH2 as an miR-138 target in this cancer type." (PMID 35505294, 2022). "Although the lysine methyltransferase activity of EZH2 is considered majorly related to its cancer regulatory role, EZH2 may also regulate HCC through other mechanisms." (PMID 36071871, 2022). "EZH2 itself is a frequent target of dysregulated expression in cancers." (PMID 36230683, 2022). "Furthermore, since various complicated signaling networks are involved in cancer progression, EZH2 inhibitors and other anti-cancer agents should be used in combination in effective cancer therapy." (PMID 35236381, 2022). "It is also well known that EZH2 stimulates the growth of cancer cells." (PMID 36619866, 2022).
cancer (continued). "The inhibition of EZH2 increases the apoptosis of cancer cells and the efficacy of cisplatin." (PMID 36077660, 2022). "Both NF-κB and EZH2 have long been regarded as crucial targets for cancer treatment." (PMID 36263173, 2022). "Excessive EZH2 expression alters histone modifications, leading to an aberrant epigenetic landscape that may contribute to cancer progression." (PMID 36195655, 2022). "As EZH2 regulates cell cycle progression, its dysregulation accelerates cell proliferation and prolongs cell survival, which may lead to carcinogenesis and cancer development." (PMID 35208478, 2022). "While inhibition of the EZH2 methyltransferase activity has been used for targeting EZH2, its role in cancer progression remains unclear." (PMID 35013218, 2022). "In this section, we provide a discussion of EZH2 regulation by circRNAs in cancer." (PMID 35236381, 2022). "For example, ASPM, ECT2, AURKA, BIRC5, CENPF, and EZH2 are amplified in several cancers." (PMID 36612203, 2022). "With this, EZH2 has emerged as an important actionable therapeutic target in such cancers." (PMID 36135315, 2022). "Of these regulatory interactions, the miR-101a/Ezh2 nexus has been established in many different cancer cells, and may operate ubiquitously in many other cell types." (PMID 35922466, 2022). "More and more evidences show that targeting EZH2 has great therapeutic potential in cancers." (PMID 35743172, 2022). "By down-regulating its target protein EZH2, methotrexate can treat cancers." (PMID 35743172, 2022). "Several studies investigated the prognostic significance of EZH2 in a myriad of cancer types." (PMID 36292072, 2022). "The introduction section demonstrated the dual role of EZH2 in cancer." (PMID 35236381, 2022). "Due to toxicity and relatively low efficiency with current EZH2 inhibitors, therefore, developing natural agents to modulate EZH2 activity may be a new approach to reduce side effects in cancer therapy." (PMID 35509102, 2022). "TIMER was used to detect RNA sequencing data in TCGA to evaluate EZH2 expression across cancers." (PMID 35659256, 2022). "It is noteworthy that EZH2 can regulate genes involved in cell cycle progression of cancer cells." (PMID 35236381, 2022). "EZH2 was found to upregulate in various cancers, such as breast cancer and prostate cancer." (PMID 36685834, 2022). "EZH2 signaling can affect immune cells in favor of cancer progression." (PMID 35236381, 2022). "Recent studies have identified EZH2 as a potential target for cancer treatment." (PMID 35085106, 2022). "The liver tissues were then extracted and divided into observation group 1 (lesion tissue specimen), observation group 2 (liver tissue around cancer lesion), and control group (normal liver tissue), and the expression activities of EZH2 and p57 genes in the three groups were analyzed." (PMID 35321452, 2022). "In addition, EZH2 can promote the secretion of inflammatory factors, regulate the cell cycle and cell proliferation, and promote the occurrence and development of cancer." (PMID 35163710, 2022). "It seems that EZH2 can affect metabolism of cancer cells in increasing their growth." (PMID 35236381, 2022). "Therefore, we propose that MEG3 exerts anti‐cancer activity through negatively regulating EZH2 in NB cells." (PMID 35257481, 2022). "The aim of this review is to present the literature data that may be relevant for future cancer treatment approaches combining the use of cisplatin and various EZH2 inhibitors." (PMID 36230683, 2022). "In conclusion, as a master regulator of transcription, EZH2 influences many features of cancer." (PMID 36230683, 2022). "In addition, cancer dependence on EZH2 sometimes relies on genetic alterations of the SWI/SNF chromatin remodeling complex, making EZH2 an epigenetic target for drugs based on synthetic lethality." (PMID 35800061, 2022). "EZH2 is recognized to play an important role in these two crucial aspects of cancer biology." (PMID 36316365, 2022).
cancer (continued). "Additive/synergistic: EZH2 knockdown increased cancer cells’ sensitivity to cisplatin." (PMID 36230683, 2022). "Interestingly, lactate itself induces the expression of GPR81 in cancer cells by transcriptional activation involving the Snail/EZH2/STAT3 transcription complex." (PMID 36230479, 2022). "It is encouraging us to explore whether tazemetostat or other EZH2 inhibitors cure cancers in an USP10-independent manner." (PMID 35627217, 2022). "Thus, the regulatory role of EZH2 in T-cells should be taken into consideration in the development of combinatory therapies in cancer." (PMID 36135315, 2022). "Like miRNAs, it has been reported that lncRNA expression can be regulated by EZH2 in cancer cells." (PMID 35236381, 2022). "In addition, the inhibition of EZH2 also sensitizes cancer cells to various other anti-cancer drugs such as HDAC inhibitors, imatinib, gemcitabine, paclitaxel, and cisplatin." (PMID 36077742, 2022). "Therefore, competitive binding between circRNAs and miRNAs is of importance for regulating EZH2 expression and subsequent impact on proliferation and invasion of cancer cells." (PMID 35236381, 2022). "Furthermore, EZH2 upregulation is in favor of chemoresistance and reducing the sensitivity of cancer cells to chemotherapy." (PMID 35236381, 2022). "EZH2 expression, which is controlled by multiple lncRNAs, is upregulated in various cancers." (PMID 35625973, 2022). "Particularly, scientific evidence has focused on the crosstalk between EZH2 and NF-κB in cancer." (PMID 36430394, 2022). "EZH2 inhibitors have shown great therapeutic potency in preclinical models of several cancer types." (PMID 35429301, 2022). "Moreover, it has been shown that the loss of and mutations in EED, EZH2, and SUZ12 promote defects during gastrulation in development, and are implicated in the development of different cancers." (PMID 36135315, 2022). "In the last decade, many studies have focused on the role of EZH2 in GB, suggesting that its inhibition could represent a valid and alternative strategy to contrast cancer progression through apoptosis and autophagy modulation." (PMID 36430394, 2022). "Therapeutic preclinical and clinical studies in cancers harboring mutations in the SWI/SNF complex subunits have recently demonstrated promising results, highlighting the fact that epigenetic regulators, such as EZH2-inhibitors, appear as a hot research topic." (PMID 35326637, 2022). "While results of clinical trials are yet to come, EZH2 inhibitors may revolutionise combinatorial immunotherapy, in particular, in cancers that normally have poor immunogenicity." (PMID 35459932, 2022). "In addition, some chemical compound that interrupts the HOTAIR—EZH2 interaction are found to inhibit cancer cell invasion and migration, which was thought to be a potential approach for targeted therapy of cancers." (PMID 36533073, 2022). "But, while EZH2 inhibitors may only have a moderate effect on the epigenetic profiles of cancer cells, aclarubicin can produce dramatic alterations, making it a promising compound for the treatment of PDAC, particularly in a combinatorial setting." (PMID 35324522, 2022). "Similarly, p16INK4A (p16 for short) encoding gene CDKN2A is a target of EZH2/PRC2 in fibroblast, mesenchymal stem cell (MSC), pancreatic beta-cell and certain cancers." (PMID 35169119, 2022). "Due to the ability of suppressing its enzymatic function, EZH2 became an anti-cancer therapy target and might bring a substantial therapeutic advance in clinical trials." (PMID 34420511, 2022). "Furthermore, it has been reported that lncRNAs recruit EZH2 to the promoter of miRNAs and other factors to reduce their expression, resulting in cancer malignancy and progression." (PMID 35236381, 2022). "It seems that lncRNA/EZH2 axis can also regulate the response of cancer cells to radiotherapy." (PMID 35236381, 2022). "Recently, efforts have been made in developing covalent inhibitors for EZH2 in cancer therapy." (PMID 35236381, 2022).
cancer (continued). "Thus, the inhibition of EZH2 using tazemetostat or GSK126 causes synthetic lethality in ARID1A-, SMARCA4-, SMARCB1-, PBRM1-deficient cancers." (PMID 36371186, 2022). "The mechanisms by which EZH2 influences cancer cell biology are diverse and entangled." (PMID 36230683, 2022). "A previous pan-cancer stemness index study identified high expression of EZH2 in ccRCC CSCs." (PMID 36077742, 2022). "Countering the induction of EZH2 expression in T cells by SLAMF7 signaling (which can be prevalent in the TME of certain cancers) are unknown factors in the TME which negatively regulate EZH2 levels." (PMID 36684449, 2022). "The poor expression of EZH2 in CD8 + T cells leads to undesirable prognosis of cancers." (PMID 35236381, 2022). "EZH2 is an epigenetic silencer of the polycomb repressor complex 2; a negative regulator of DNA damage-related proteins of ATM involved in the X-ray-induced DNA damage; and has been associated with the prognosis of several cancer entities." (PMID 35160302, 2022). "Antagonistic: Inhibition of EZH2 with GSK126 increased cancer cell resistance to cisplatin." (PMID 36230683, 2022). "Clinical trials for EZH2 inhibitors are already underway in the field of cancer." (PMID 36313363, 2022). "Therefore, several strategies (outlined in the next section) have been developed to tackle the increased expression/activity of EZH2 in cancers." (PMID 36230683, 2022). "EZH2 expression across cancers was explored through Oncomine, HPA, and GEPIA2." (PMID 35659256, 2022). "Its ability to form non-PRC2 complexes significantly broadens the spectrum of target genes potentially controlled by EZH2 and might at least partially explain the multiple and controversial EZH2 functions described in cancer." (PMID 35884510, 2022). "ARID1A mutations negatively impact DNA damage repair in cancer cells and while their role in regulating sensitivity to checkpoint inhibitors is unclear, they have been also shown to sensitize cancer cells to PARP inhibition as well as to EZH2 inhibition." (PMID 35664801, 2022). "Clinical studies have confirmed the role of EZH2 in cancer prognosis." (PMID 35236381, 2022). "This study proposes that some of the silibinin’s anti-cancer effects may be mediated by epigenetic pathways regulated by altered EZH2 activity." (PMID 35327559, 2022). "EZH2 is responsible for trimethylation of the histone H3 at Lys 27 (H3K27me3) and functions as an epigenetic regulator of transcription and is often overexpressed in cancer." (PMID 36138075, 2022). "Studies have reported that the miR-124-3p/EZH2 signaling pathway is involved in cancer." (PMID 36467610, 2022). "EZH2 is suggested to be a main driver of cancer cells’ immunoediting which leads to immune escape." (PMID 36230683, 2022). "As such, efforts to therapeutically target EZH2 have generally focused on inhibition of its methyltransferase activity, although it remains undefined whether modulation of H3K27 trimethylation is the prominent mechanism whereby EZH2 promotes cancer." (PMID 35013218, 2022). "Furthermore, surface modification of nanoparticles, for instance by RGD peptide, can enhance the selectivity of nanoparticles towards cancer cells and in EZH2 silencing." (PMID 35236381, 2022). "Many studies have shown that some lncRNAs could recruit EZH2 to participate in the transcriptional repression of target genes in multiple cancers and diseases." (PMID 36087568, 2022). "EZH2 is dysregulated in various types of cancer, including brain tumors." (PMID 35197928, 2022). "EZH2 also regulates the response of cancer cells to therapy." (PMID 35236381, 2022). "Additionally, the prognostic value of EZH2 analysis across cancers was based on the GEPIA2, TCGA portal, Kaplan–Meier Plotter, and LOGpc databases." (PMID 35659256, 2022). "Since EZH2 regulates cell cycle progression, the dysregulation of EZH2 increases cell proliferation and prolongs cell survival, which may lead to cancer formation and progression." (PMID 36291769, 2022).